MRAP2 (melanocortin 2 receptor accessory protein 2)
Diseases named in the same sentence as MRAP2 in open-access papers (continued):
Sharing a sentence is not in itself a finding about the gene and the disease.
Obesity (continued). "Mrap2–/– mice develop severe obesity, although they lack the early-onset hyperphagia of Mc4r–/– mice, which brings into question the extent to which MRAP2 qualitatively and quantitatively interacts with MC4R in vivo." (PMID 36692018, 2023). "Germinal deletion of MRAP2, in Mrap2–/– mice, leads to obesity, although to a lesser extent than that observed in Mc4r–/– mice." (PMID 36692018, 2023). "MRAP2 knock-out (KO) mice develop severe early onset obesity because MRAP2 is involved in the control of food intake." (PMID 35327666, 2022). "Mutations of arginine 125 in histidine (R125H) or cysteine (R125C) have been detected in the conserved C-terminal region of MRAP2 in humans, where they are correlated with an extreme obesity phenotype." (PMID 36077245, 2022). "In the Mammalian Phenotype database (MPD), multiple phenotype terms are related to obesity or body size for MRAP2, e.g., “increased body weight”, “obese”, “increased total body fat amount”, and “increased food intake”." (PMID 35168569, 2022). "Results obtained with the MRAP2 mutants R125H and R125C, which are found in human patients with extreme obesity, and mouse MRAP2, in which arginine 125 is normally replaced by histidine, were compared with those obtained with human MRAP2." (PMID 36077245, 2022). "Inherited obesity and polygenic obesity (stemming from multiple and synergistic polymorphisms) are thought to involve brain, signaling, and nervous system genes such as NTRK2, KCNQ1, MRAP2, and ADCY3 that regulate satiety and thermo-caloric energy balance." (PMID 36143948, 2022). "As in mammals and birds, MC4R, AgRP, POMC, and MRAP2 have also been identified in some teleost species, and these molecules likely play similar roles in feeding, growth, and obesity within the hypothalamus." (PMID 32987823, 2020). "Whilst female mice overexpressing MRAP2 in PVN MC4R neurons demonstrate overt protection against obesity on a chow diet, this phenotype was only observed in male mice after challenge with high fat diet." (PMID 30352741, 2018). "Deletion of MRAP2 in Sim-1 expressing neurons leads to obesity in mice to a similar extent as in global Mrap2−/− animals pointing to these neurons, located also in the PVN, as key targets of MRAP2 action in metabolism regulation." (PMID 30352741, 2018). "As previously reported, Mrap2 knockout (KO) mice develop obesity and their weight start diverging from wild-type (WT) animals between 9 and 11 weeks of age10." (PMID 28959025, 2017). "In other words, losing the function of both MRAP2 and MC4R causes a milder obesity than losing the function of MC4R alone, suggesting that MRAP2 can promote weight gain through a mechanism that is distinct and independent from the regulation of the MC4R." (PMID 26829592, 2016). "Mrap2tm1a/tm1a mutant mice on both C57/BL6N and 129/Sv background display severe early-onset obesity with a significantly increased fat mass, consistent with a recent report of Mrap2-knockout mice." (PMID 27106110, 2016). "Whole body deletion and targeted brain specific deletion of the Mrap2 gene result in severe obesity in mice." (PMID 26113808, 2015). "Phenotypically, global Mrap2 KO mice on an sv129 genetic background fed a chow ad libitum diet develop severe obesity at a young age and were found to be significantly heavier than their wild type counterparts at approximately 6 weeks of age." (PMID 26113808, 2015). "Selective knockout of Mrap2 in neurons expressing Sim1 also exhibit obesity, similar to global knockout of Mrap2, consistent with the idea that Sim1 expressing neurons are key regulators of energy balance." (PMID 25825681, 2015). "We investigate whether obesity-associated variants of MRAP2 alter their ability to modulate MC4R and GHSR signalling as a possible mechanistic link to the development of obesity." (PMID 41758604, 2026). "Targeted deletion of Mrap2 leads to early-onset severe obesity in mice." (PMID 41596694, 2026).
Obesity (continued). "The MRAP2 N88Y mutation, identified in one individual with obesity, has not been functionally characterized and our studies indicate it reduces MC4R activity by both the cAMP and IP3 signaling pathways." (PMID 39807633, 2025). "Loss of MRAP2 function leads to decreased MC4R signaling and obesity in mouse models." (PMID 39237720, 2025). "Obesity and metabolic disorders may be risk factors for AAA, with MRAP2 regulating appetite and energy balance, potentially indirectly affecting AAA-related risk factors such as hypertension and atherosclerosis." (PMID 39600608, 2024). "Mutations in MRAP2 and MC4R cause obesity in both humans and mice." (PMID 35588128, 2022). "Mutations of MRAP2 are associated with obesity but it has not been found to be linked to FGD as MRAP1, suggesting that MRAP1 and MRAP2 are not functionally interchangeable." (PMID 33716796, 2021). "Mice with whole body and brain-specific deletion of Mrap2 also have early-onset severe obesity." (PMID 32922362, 2020). "While the modestly decreased EE may contribute to obesity in the Cpe-/-, and Mrap2-/- mice, food intake and other factors are likely the primary drivers as reported." (PMID 32356724, 2020). "Mice with global MRAP2 deletion and conditional MRAP2 deletion in SIM1 expressing neurons developed marked obesity, while rare loss-of-function or missense heterozygous variants in MRAP2 were identified in humans with severe early-onset obesity." (PMID 30352741, 2018). "The phenotype of gross, early onset obesity without detectable change of food intake and energy expenditure, replicated in an independent Mrap2 deficient model, is particularly intriguing." (PMID 30352741, 2018). "Mice with germline deletion of Mrap2 are characterized by obesity and increased linear growth." (PMID 30134862, 2018). "Both global and brain-specific deletion of Mrap2 in mice results in severe obesity." (PMID 27106110, 2016). "Although MRAP2 has been shown to interact with MC4R, a G protein-coupled receptor with an established role in energy homeostasis, appetite regulation and lipid metabolism, the mechanisms through which loss of MRAP2 causes obesity remains uncertain." (PMID 27106110, 2016). "MRAP2 is an important regulator of energy homeostasis and Mrap2 KO mice develop severe obesity." (PMID 26829592, 2016). "Mice of a 129/Sv genetic background, less prone to developing obesity-related co-morbidity, were used to reveal the effect of Mrap2 deficiency without secondary changes caused by hyperinsulinaemia and/or elevated glucose." (PMID 27106110, 2016). "Other gene mutations in heterozygous states (MRAP2, MC3R, SRC1, KSR2) are associated with obesity and may exhibit autosomal dominant inheritance; however, the clinical phenotype depends on the degree of genetic penetrance and interactions with other genetic and/or environmental factors." (PMID 41751424, 2026). "Taken together, these data reinforce the biological plausibility that disruption of MRAP2-mediated GPCR signaling contributes to obesity and related metabolic disturbances, but the current functional evidence is incomplete and should be regarded as hypothesis-generating." (PMID 41596694, 2026). "Moreover, the dysregulation of the prokineticin system in obesity could be due to the presence of mutations in the accessory PKR protein, the accessory melanocortin 2 receptor protein (MRAP2)." (PMID 39459554, 2024). "Specifically, we found that inactivating Mrap2 specifically in MC4R-expressing neurons causes, like Mc4R loss-of-function, early-onset hyperphagia and obesity, whereas germline inactivation of Mrap2 caused a milder phenotype, with late-onset hyperphagia and obesity." (PMID 36692018, 2023). "Additionally, the melanocortin accessory protein MRAP2 has been shown to modulate trafficking and function of MC4R to a level that is physiologically significant, as transgenic mice with whole-body deletion and brain-specific deletion of Mrap2 develop severe obesity at a young age." (PMID 33761344, 2021).
Obesity (continued). "Finally, this study illustrates the important role of the interaction of PKR1 and MRAP2 in the regulation of energy homeostasis and suggests that this complex may be a valuable new target for the treatment of obesity." (PMID 26829592, 2016). "The changes observed in white fat were only found in females and are thus unlikely to be the primary cause of MRAP2-associated obesity, although this might explain the greater severity of obesity in females." (PMID 27106110, 2016). "MRAP2 potentiates MC4R signaling in vitro and the deletion of MC4R and MRAP2 both develop severe obesity in vivo." (PMID 35311242, 2022). "Mouse models depleted of MRAP2 have extreme obesity, increased fat mass and visceral adiposity, analogous to MC4R knockout mice; while double knockouts of MRAP2 and MC4R further demonstrated that MRAP2 facilitates the action of MC4R, but that there are also MC4R-independent mechanisms." (PMID 39807633, 2025). "The melanocortin pathway which is linked to both melanin synthesis and obesity seems to be altered with unclear significance, as the sex difference in POMC, DCT/TYRP2, and MRAP2 was observed but with no clear direction." (PMID 34436011, 2021). "Nonsynonymous MRAP2 variants have been detected in obese patients, but not in normal weight controls in a meta-analysis, and Mrap2-deletion leads to obesity in mice." (PMID 33807040, 2021). "However, no large-scale research has focused on MRAP2 and obesity through meta-analysis to reliably assess gene-disease associations." (PMID 41596694, 2026). "Besides SIM1 and MC4R, the haploinsufficiency of proprotein convertase 1 (PCSK1), melanocortin 2 receptor accessory protein 2 (MRAP2) in the brain, iroquois homeobox 3 (IRX3) in fat or uncoupling protein 3 (UCP3) in mitochondria are also responsible for human obesity." (PMID 31124015, 2019). "It will be important to investigate whether MRAP2 variants affect multiple aspects of GPCR signaling, because inactivating mutations in MC4R that contribute to obesity may not affect canonical signaling but can affect internalization, homodimerization or other G protein pathways." (PMID 41401256, 2025). "Finally, it is also possible that molecules that interfere with the interaction of GHSR1a with MRAP2 could reduce ghrelin action centrally to treat obesity without having deleterious cardiovascular effects." (PMID 35605660, 2022). "Unlike the global Mrap2 KO animals, AGRPCRE/MRAP2fl/fl mice do not develop obesity." (PMID 28959025, 2017).
Hypertension (9 papers, 2023 to 2026). The presence of chronic increased pressure in the systemic arterial system. "MRAP2 mice lack the early-onset hyperphagia of MC4R knockout mice, and humans with MRAP2 genetic variants exhibit hyperglycaemia, hypertension and high blood cholesterol more frequently than those with MC4R mutations." (PMID 39574659, 2024). "Loss-of-function MRAP2 variants are also implicated in hypertension and hyperglycemia." (PMID 41596694, 2026). "Hyperglycaemia and hypertension have been reported to occur more commonly in individuals with MRAP2 mutations than in those with MC4R mutations, which led to the suggestion that MRAP2 variants may affect signaling by other GPCRs." (PMID 41401256, 2025). "One group also reported hyperglycaemia and hypertension occurred more commonly in individuals with MRAP2 mutations than in those with MC4R and suggested that MRAP2 variants may affect signaling by other GPCRs." (PMID 39574659, 2024). "MRAP2 knockout mice lack the early-onset hyperphagia of MC4R knockout mice, and humans with MRAP2 genetic variants exhibit hyperglycaemia, hypertension and high blood cholesterol more frequently than those with MC4R mutations." (PMID 41401256, 2025).
atherosclerosis (2 papers, 2019 to 2024). A disease characterized by the build-up of fatty material and calcium deposition in the arterial wall resulting in partial or complete occlusion of the arterial lumen. "Finally, ACP5, MRAP2, and MME were found to show associations with both atherosclerosis and lncRNA-H19." (PMID 30778327, 2019).
infertile (2 papers, 2020 to 2023). "In contrast, MRAP2, upregulated by kaempferol and progesterone treatments, has been identified as downregulated in human pre-receptive and receptive endometria and upregulated in the endometria of infertile patients." (PMID 36986136, 2023). "In addition, we also noticed some genes which are related with Piétrain economical traits: MRAP2 can regulate the energy homeostasis machinery; CLGN, an important modulator in spermatogenesis and infertility." (PMID 32455573, 2020). "However, we observed several genes which were related to Piétrain specific economic traits around ROH regions, such as MRAP2 which was related to energy homeostasis machinery, and CLGN which was involved in the control of spermatogenesis and infertility." (PMID 32455573, 2020).
breast carcinoma (1 paper, 2024). "In addition, the expression of ADRB1 and MRAP2 in breast cancer patients was significantly lower than in normal samples (P < 0.05)." (PMID 38676834, 2024).
obesity syndromes (1 paper, 2022). "Both MRAP2- and MC4R-deficient backgrounds develop severe obesity syndrome in human and murine models." (PMID 35311242, 2022). "MRAP2 is highly expressed in the hypothalamus, especially the paraventricular nucleus (PVN), and has been linked to mammalian obesity syndromes." (PMID 35311242, 2022).
cancer (2 papers, 2021 to 2024). A tumor composed of atypical neoplastic, often pleomorphic cells that invade other tissues. "Moreover, ADRB1, CCDC28B, MRAP2, SERPINA12, and WT1 were able to effectively distinguish between normal breast tissue and cancer tissue (AUC > 0.6)." (PMID 38676834, 2024).
MRAP2 also shares sentences with these, for which no sentence is quoted: hyperglycaemia (7 papers); metabolic disorders (3); diabetes (2); Bardet-Biedl syndrome (1); Type 2 Diabetes (1).